ARID1A (AT-rich interaction domain 1A)
Diseases named in the same sentence as ARID1A in open-access papers (continued):
Sharing a sentence is not in itself a finding about the gene and the disease.
tumor (continued). "Because homogeneous loss within the tumour is characteristic to EBV-associated GC and because ARID1A mutations are present in chronically inflamed and non-neoplastic gastric mucosa infected by H. pylori, abnormality of ARID1A is considered an early event in carcinogenesis." (PMID 35053587, 2022). "Finally, in order to determine the effects of ARID1A downregulation on tumour growth in vivo, we subcutaneously engrafted ARID1A knockdown and their parental IK cells in immunodeficient mice (NSG), to generate subcutaneous tumours." (PMID 35167193, 2022). "NEC-like IDH2 and NEC-like SMARCA4/ARID1A tumors also demonstrated strong overexpression of proteins specific for neurons or cells of the diffuse neuroendocrine system such as UCHL1, CRMP1 and ENO2, strongly indicating a neuroendocrine differentiation for both tumor classes." (PMID 36443295, 2022). "The median progression-free survival of patients with altered ARID1A was significantly longer than that of patients with wild-type ARID1A in terms of response to ICB therapy, regardless of microsatellite instability (MSI) and tumor mutation burden (TMB) statuses." (PMID 33419967, 2021). "However, the clinical significance of such differential expressions and the function of the ARID1A protein remain undefined due to the lack of studies using fresh human tumor samples." (PMID 33578810, 2021). "Intriguingly, in contrast to the initial tumour development stages where ARID1A was shown to support tumorigenesis, the authors also demonstrated that both heterozygous and homozygous ARID1A deletions accelerated HCC progression and metastasis following initial tumour establishment." (PMID 32162380, 2020). "Moreover, since ARID1A and ANXA1 contribute to poorer prognosis and pre-exist in treatment-naïve tumours, they may assist in identifying which HER-2+ patients might require a different therapeutic approach." (PMID 33276477, 2020). "Although the results suggest that ARID1A and ARID1B may participate in the modulation of the TIME and are associated with the elevations in tumor mutability and PD-L1 expression, no molecular mechanism was explored in this research." (PMID 32791957, 2020). "Although the roles of H1ST1H1E and ARID1A in immune cells have not been fully identified, changes mediated by epigenetic regulations may alter the function of T cells in anti‐tumor immunity." (PMID 33252851, 2020). "In addition, the HR gene panel without ARID1A remained independently associated with longer overall survival after adjusting for high TMB, type of ICI administered, and tumor type (p = 0.015; hazard ratio, 1.36; 95% CI, 1.06–1.74)." (PMID 32676589, 2020). "Although the causative action of ARID1A has been questioned because siRNA mediated knockdown of BAF250a in OCCC lines (wild type for ARID1A) showed no increase in either pAKT-Thr308 or pAKT-S473 indicating that pAKT in tumor tissues was indirectly regulated by BAF250a expression." (PMID 31731647, 2019). "However, in vivo evidence that ARID1A functions as a tumor suppressor in HCC has not yet been provided." (PMID 26569409, 2015). "However, the clinical significance of such differential expression and the function of the ARID1A protein remain undefined due to the lack of studies using fresh human tumor samples." (PMID 22808142, 2012). "However, because chromatin regulators such as ARID1A often exhibit context-specific tumor suppressive and oncogenic roles in liver cancer development, it is unclear whether MLL3 is a bona fide tumor suppressor in HCC." (PMID 37261974, 2023). "Therefore, we explored whether ARID1A and YAP influence tumour metastasis in vivo." (PMID 37173914, 2023). "Interestingly, in the subgroup analysis, positive PD-L1 immunostaining in tumor cells was associated with better PFS in patients not carrying activation of DNA damage repair components, as defined by the presence of ARID1A mutations and negative pATM expression." (PMID 36980292, 2023).
tumor (continued). "One tumor (IGR-03) diagnosed as SCCOHT did not exhibit a SMARCA4 mutation but instead, harbored concomitant and potentially biallelic loss-of-function alterations in two other SWI/SNF genes: ARID1A (two frameshifts—p.Q555fs and p.T1004fs) and ARID1B (stop gained R1944*)." (PMID 32575483, 2020). "Interestingly, one MC type line, HOV29T, showed ARID1A negative, which might indicate that the origin of this tumor is the same as that of CC and EM type tumors." (PMID 31248002, 2019). "Although the scale of anti-tumour effect in TOV21G xenografts was not as profound as in HCT116 ARID1A−/− xenografts, the effect of ATRi in this setting did suggest that the ARID1A/ATR synthetic lethality could be exploited in vivo and warrants further investigation." (PMID 27958275, 2016). "AT-rich interaction domain 1 A gene (ARID1A), a subunit of the switch/sucrose non-fermentable (SWI/SNF) complex, regulates immunosuppressive tumor microenvironment." (PMID 42191692, 2026). "While conventional cancer driver genes of sporadic PC were not involved in our case, deletions were identified in the tumor suppressor genes CDKN2A, LATS1, ARID1A, and ARID1B." (PMID 40362680, 2025). "ARID1A is a component of the SWI/SNF (Switch/Sucrose Nonfermentable) chromatin remodeling complex and functions as a tumor suppressor gene." (PMID 40281353, 2025). "Lastly, we established subcutaneous tumor models of the VOA1066 cell line (cell line xenograft (CDX)) and a novel PDX, XVOA14590, derived from a human DDEC primary tumor lacking both ARID1A and ARID1B expression." (PMID 41279405, 2025). "These researchers found that mice with ARID1A-expressing tumors, PARP inhibition did not have any additional anti-tumor benefits that irradiation did not have." (PMID 40429787, 2025). "We noted that the absence of ARID1A in both T24 and JMSU‐1 tumor cells strongly induced interferon (IFN) type I and II pathways, but less prominently in the two normal‐like lines." (PMID 40170512, 2025). "The latest research confirmed the role of ARID1A, a member of the switch/sucrose nonfermenting (SWI/SNF) chromatin remodeling complex, which serves as a tumor suppressor in LUAD." (PMID 36869329, 2023). "The concept of selective vulnerability of ARID1A deficient CRC cells to ATRi was further tested in an ex vivo system by using the ATP-tumor chemosensitivity assay (ATP-TCA) in cells from untreated CRC patients, with and without ARID1A expression." (PMID 36249060, 2022). "ARID1A is a member of the SWI/SNF (SWIft/Sucrose Non-Fermentable) complex of chromatin remodelers and is considered a tumor suppressor." (PMID 36082022, 2022). "This indicated that the increased number of PD1+ TILs in ARID1A-low GBC tumors was not attributed to an overall increase in the number of TILs, but it was potentially the result of high PD-L1 expression in tumor tissue." (PMID 35198440, 2022). "The majority of DDEC/UEC harbor inactivating mutations involving core components of SWI/SNF complex with SMARCA4 and ARID1A/ARID1B being most commonly inactivated, resulting in absent expression of corresponding proteins in the undifferentiated tumor." (PMID 33125840, 2021). "The study concluded that ARID1A inactivation is not sufficient to initiate the carcinogenesis process, the alteration of the PI3K/PTEN/AKT pathway being a prerequisite in promoting tumor progression." (PMID 31126056, 2019).
tumor (continued). "In this experiment, early initiation of VX-970 treatment also dramatically slowed the growth of ARID1A−/− tumours (P=0.015, ANOVA), but did not impair ARID1A+/+ xenografts (P=0.63, ANOVA)." (PMID 27958275, 2016). "ARID1A is one of the subunits of the Switch/Sucrose Non-Fermentable (SWI/SNF) chromatin remodeling complex and is currently thought to behave like a tumor suppressor gene." (PMID 26468873, 2015). "An increase in tumor‐infiltrating lymphocytes was noted in a study of ovarian cancer in syngeneic mice, while inhibited CD8+ T cell infiltration was seen in triple‐negative breast cancer patients with low ARID1A expression." (PMID 40170512, 2025). "However, in some cases, SNVs were seen only in the tumor and not in the corresponding CSF cfDNA, including SNVs in ROBO1, APC, PIK3CA or ARID1A." (PMID 37444642, 2023). "Instead, they identified only four genes exhibiting a high non-synonymous to synonymous mutation ratio in non-dysplastic IBD, including PIGR, ZC3H12A, and two tumor suppressors, the SWI/SNF family chromatin remodeling gene ARID1A and the ubiquitin ligase complex gene FBXW7." (PMID 37884500, 2023). "ARID1A is a Switch/Sucrose non-fermentable (SWI/SNF) chromatin remodeling complex subunit that regulates many cellular processes such as development, proliferation, differentiation, DNA repair, and tumor suppression." (PMID 29890703, 2018). "However, as we demonstrate here in a large tumor dataset, we found that GLS1 is not overexpressed in clinical specimens of OCCC that are negative for ARID1A and that on the contrary, ARID1A-positive tumors have higher levels of GLS1 as compared to patients who are ARID1A negative." (PMID 36082022, 2022). "Although we were not able to include tumors from this class in our proteomics study due to insufficient quantities of tumor tissue, we did not detect immunohistochemical expression of the neuroendocrine and neuronal markers that were upregulated in NEC-like IDH2 and NEC-like SMARCA4/ARID1A tumors." (PMID 36443295, 2022). "Mechanically, cancer cells lacking ARID1A expression have higher phosphorylation levels of AKT-Thr308 and AKT-Ser473, which is contrary to those in ARID1A-knockdown OCCC cell lines, indicating that phosphorylation of AKT in tumor tissues is regulated by ARID1A indirectly." (PMID 34671561, 2021). "While studies to explore the role of ARID1A in later stage PDAC progression are in progress, the irreversibility of the Kras-induced PanIN phenotype indicates that impaired SWI/SNF function may not be required for tumor maintenance." (PMID 30014851, 2018).
cancer (761 papers, 2011 to 2026). A tumor composed of atypical neoplastic, often pleomorphic cells that invade other tissues. "Our work revolves around the long‐standing paradox of how ARID1A mutations in non‐malignant tissues collaborate with environmental carcinogens to initiate cancer." (PMID 41133886, 2026). "It is found that aristolochic acid I accelerated liver tumorigenesis in ARID1A‐deficient context by impairing nucleotide excision repair and enhancing carcinogen bioactivation, revealing key mechanisms driving cancer development." (PMID 41133886, 2026). "This point of view is reinforced by current findings that the role of ARID1A is highly context-dependent, varying with cancer stage and mutations." (PMID 41514650, 2025). "Analysis of the MSK cancer panel data of 2022 revealed ARID1A mutations to be foremost truncating, which leads to inactivation and protein loss through rapid degradation." (PMID 40170512, 2025). "Here we define the biochemical and chromatin regulatory mechanisms underlying ARID1A/B dual-deficient DDEC/UEC cancers, and inform new potential therapeutic approaches." (PMID 41279405, 2025). "This synthetic lethality approach exploits the DNA repair deficiencies in ARID1A-mutant cancers, offering a targeted treatment strategy." (PMID 39858102, 2025). "In this study, we discovered the role of ARID1A deficiency in cancer progression and Osimertinib resistance in LUAD." (PMID 39773749, 2025). "While somatic mutations occur in many cancers, heterozygous germline mutations of ARID1A or ARID1B have been linked to the neurodevelopmental disorder Coffin‐Siris syndrome." (PMID 40170512, 2025). "Given the high frequency of ARID1A loss or inactivation in cancer, the exploitation of anticancer therapeutics based on ARID1A status has been investigated." (PMID 40750787, 2025). "For instance, cancer cells with inactivating mutations in ARID1A become highly dependent on the opposing polycomb repressive complex 2 (PRC2) component, EZH2, creating a therapeutic vulnerability." (PMID 40940815, 2025). "Mutational inactivation of the tumor suppressor gene ARID1A is a key driver of tumorigenesis in various types of cancer, making it a promising therapeutic target for anticancer drug development." (PMID 41360780, 2025). "These non-cancer studies underline the context-specific role of ARID1A to impact gene expression that influences the cell fate or stemness of a given cancer cell." (PMID 40429787, 2025). "Through whole-exome sequencing and analysis using the cBioPortal cancer genomic database, their study identified ARID1A as one of two key high-risk genes." (PMID 41001036, 2025). "Predicting how ARID1A loss impacts cancer therapy response is challenging because it influences many cellular pathways." (PMID 40938753, 2025). "Surveying 829 polyclonal gastric microbiopsies by targeted sequencing, we find somatic 'driver' mutations in a distinctive repertoire of known cancer genes, including ARID1A, ARID1B, ARID2, CTNNB1 and KDM6A." (PMID 40108450, 2025). "Together, these findings demonstrated that Arid1a deletion in combination with K‐ras mutation reprograms cancer cell metabolism and enhances fatty acid biosynthesis, suggesting a novel avenue for targeted therapy." (PMID 40621620, 2025). "Previous reports have shown that ARID1A loss tends to activate the PI3K/AKT signaling pathway in some cancers." (PMID 41360780, 2025).
cancer (continued). "AT-interacting domain-rich protein 1A (ARID1A) and ARID1B (ARID1A/B), a pivotal subunit, have significant relevance in cancer management because they are frequently mutated in a broad range of cancer types." (PMID 40087883, 2025). "Mutational inactivation of ARID1A is found in various type of cancers, and its loss leads to several tumorigenic consequences, including enhanced proliferation and resistance to apoptosis." (PMID 41360780, 2025). "ARID1A-deficient cancer cells exhibit increased type I interferons (IFN) response signaling, which promotes CD8+ T-cell recruitment and cytolytic activity." (PMID 40750787, 2025). "In this study, our results showed that inhibiting MDM2 can indeed attenuate the enhanced malignant phenotypes induced by ARID1A deficiency, including cancer progression and Osimertinib resistance." (PMID 39773749, 2025). "For instance, cancer cells with ARID1A mutations become highly dependent on the activity of enhancer of zeste homolog 2 (EZH2), a core component of the opposing PRC2 complex." (PMID 40940815, 2025). "In approximately 30%–50% of ARID1A-mutated cancers, intact ARID1A protein expression has been observed, although its clinical significance remains underexplored." (PMID 40761291, 2025). "As more pathogenic variants of ARID1A are identified and more targeted cancer therapies are developed there will be molecular profiles involving ARID1A that guide clinical decisions that result in better outcomes for patients with cancer." (PMID 40429787, 2025). "Applying such an approach to ARID1A mutants identified local exclusion of immune cells, a recognised cancer hallmark, as a feature of histologically normal epithelial clones." (PMID 39920335, 2025). "Our findings uncover many opportunities for therapeutic interventions in ARID1A-deficient cancers, which represent ∼8% of cases across all malignancies." (PMID 40239999, 2025). "On the other hand, the sensitivity of ARID1A-deficient cancer cell lines to CBP/p300 dual inhibitors was intermediate between SWI/SNF WTs and the sensitive genotypes (SMARCA4/SMARCA2-deficient and SS18–SSX fusion)." (PMID 39625239, 2025). "Of the genomic alterations involving alleles encoding BAF subunits, those occurring at the SMARCA4 and ARID1A loci have been the most thoroughly investigated in human cancer." (PMID 41387924, 2025). "Seemingly paradoxical is the observation that loss of ARID1A mildly compromises cell fitness in normal cells, but inactivating ARID1A mutations are broadly selected across cancers." (PMID 40239999, 2025). "ARID1A and its paralog ARID1B occupy the same position within the BAF complex and can functionally compensate for each other, which makes ARID1B essential to cancer cells following ARID1A mutation." (PMID 41387924, 2025). "Emerging evidence indicates that ARID1A mutations serve as an independent prognostic biomarker, with loss-of-function variants significantly associated with reduced cancer-specific survival, increased recurrence rates and diminished therapeutic response." (PMID 41001036, 2025). "ARID1A mutations are prevalent in various cancers, and the mutated cells are sensitive to PARPi inhibitors." (PMID 39779467, 2025). "First, ARID1A loss in cancer cells impairs the DNA damage checkpoint and increases sensitivity to poly ADP‐ribose polymerase (PARP) inhibitors." (PMID 40621620, 2025). "ARID1A mutations exhibit diverse prognostic significance across different types of cancer, though the data on this topic remains somewhat controversial." (PMID 40429787, 2025). "This will become more apparent in cases of synthetic lethality where the loss of ARID1A makes cancer cells more susceptible to therapies such as ATM and PARP inhibitors." (PMID 40429787, 2025).